CD47 (CD47 molecule)
Diseases named in the same sentence as CD47 in open-access papers (continued):
Sharing a sentence is not in itself a finding about the gene and the disease.
tumor (continued). "CD47 overexpression occurs in other PTCL subtypes, including PTCL-NOS and ALCL, although expression levels vary across tumor samples." (PMID 41295262, 2025). "In multiple in vivo models, CD47E-CAR T-cells administered alongside a CD47-blocking mAb exhibited increased persistence, enhanced macrophage infiltration into the TME, and improved anti-tumor activity." (PMID 41019052, 2025). "Mechanistic insights indicate that arsenic sulfide inhibits STAT3 phosphorylation, reduces THBS1 transcription, thereby disrupting the binding between tumor cell THBS1 and T cell CD47, consequently enhancing anti-PD-1 efficacy." (PMID 41019041, 2025). "TUG1 regulates the expression of PD-L1 and CD47 by adsorbing miR-141 and miR-340, respectively, and interacts with YBX1 to promote their transcriptional upregulation, ultimately facilitating tumor immune evasion." (PMID 40352941, 2025). "In both cases, blocking the CD47 checkpoint enhanced CAR T-cell function and anti-tumor activity, including in models with tumor antigen heterogeneity." (PMID 41019052, 2025). "Our experiments confirmed that reducing HIF-1α while increasing CD47 in GBM cells significantly enhances malignant proliferation, colony formation and tumor cell migration, indicating that HIF-1α can modulate GBM characteristics via the CD47 protein." (PMID 39781344, 2025). "Blocking CD47–SIRPα with the decoy receptor TTI-621 enhances macrophage phagocytosis and reduces tumor burden." (PMID 40963633, 2025). "The stiff subtype exhibited significantly increased tumor mutual burden and T cell follicle helper cell levels compared with the soft subtype, along with the expression of CTLA4, CD276, CD47, and TNFRSF25." (PMID 40277910, 2025). "SIRPα is not expressed in normal astrocytes but exhibits functional expression in astrocytomas, potentially participating in cell adhesion and signaling through CD47-dependent phosphorylation and SHP-2 recruitment, thereby influencing tumor invasiveness." (PMID 40589735, 2025). "Considering the differences in tumor characteristics in antagonizing anti-tumor immunity, the combination of NDV and CD47 blockade was also explored in KPC PDAC." (PMID 41322194, 2025). "The CD47-SIRPa axis promotes immune evasion in HCC and a cold HCC phenotype since overexpression of CD47 allows HCC tumor cells to transmit inhibitory signals upon binding with SIRPa." (PMID 41012682, 2025). "This strategy not only blocks the CD47-SIRPα axis to enhance macrophage phagocytosis, but also delivers DM1 for direct tumor killing that releases tumor antigens for immune presentation." (PMID 41256852, 2025). "Thus, blocking CD47 expression on cancer cells may enhance the anti-tumor immune response." (PMID 40296909, 2025). "To evaluate the impact of NDV infection on the expression of anti-phagocytic CD47 and the pro-phagocytic surface calreticulin (CRT), we infected three murine tumor cell lines with GFP expressing NDV." (PMID 41322194, 2025). "Other checkpoints, such as CD47 and CD73, help tumor cells evade immune detection by inhibiting phagocytosis, suppressing antigen-presenting cells, and altering immune cell functions." (PMID 40948940, 2025). "Tumor cells can evade TAM clearance by overexpressing antiphagocytic surface proteins known as “don't eat me” signals, such as, CD47 and CD24." (PMID 41354057, 2025). "Blocking the CD47-SIRPα axis significantly enhances macrophage-mediated tumor phagocytosis, which has been shown to be effective in EOC models, and several anti-CD47 monoclonal antibodies (e.g., magrolimab) are in clinical trials." (PMID 41050676, 2025). "Following Kaplan-Meier analysis, a significant survival benefit was only observed in KPC-tumor-bearing mice treated with NDV-αCD47, compared to those treated with anti-CD47." (PMID 41322194, 2025).
tumor (continued). "While direct evidence linking other pathways to ICP regulation in CSCs is still limited, several studies have independently shown an association between PI3K/AKT, PTEN, EGFR and stemness and ICP (e.g., CD47, PD-L1 and TIM3) regulation in bulk tumor cells." (PMID 41233805, 2025). "In the mice model of partial tumor resection mediated by CD47‐targeted OMI, compared to group A (immune therapy alone), group C (NIR‐PIT treatment) mice showed a reduced tumor recurrence rate after NIR‐PIT intervention." (PMID 40385528, 2025). "Phagocytosis regulators exhibited differential expression across various female-specific cancers, with key genes such as CD47 and FOXO1 playing significant roles in modulating tumor progression." (PMID 40396172, 2025). "Within the tumor microenvironment (TME), macrophage phagocytic activity is finely regulated, and targeting “don’t eat me” signals (e.g., CD47) or enhancing “eat me” signals has emerged as a crucial immunotherapeutic strategy." (PMID 41459510, 2025). "They revealed the connection between TME remodelling and tumour metastasis through the distribution of PROM1+ and CD47+ cancer stem cells, providing new insights for potential tumour interventions." (PMID 39924620, 2025). "The CD47–TSP-1 axis suppresses angiogenesis via VEGFR2 inhibition, thereby limiting tumor growth and metastasis, modulating inflammatory responses, and promoting tissue regeneration." (PMID 40948940, 2025). "As was observed in vitro, NDV infection led to an increase in the number of GFP+ CD47+, CD45+ SIRPα+, and CRT+ GFP+ tumor cells." (PMID 41322194, 2025). "Although CD47 inhibition has demonstrated potential against GBM, complete tumor remission remains limited." (PMID 40800581, 2025). "Twenty ADG tumors with matched normal brain tissues were further analyzed; the expression levels of CD47 and TIGIT in tumor tissues were higher than those in matched adjacent normal brain tissues (P < 0.0001)." (PMID 38404571, 2024). "The anti-CD47 monoclonal antibody B6H12 has been proven to induce macrophage-mediated phagocytosis, suppress tumor growth, and augment the efficacy of chemotherapy in HCC." (PMID 39170620, 2024). "The hMnO2 core effectively alleviated tumor hypoxia by inducing decomposition of tumor endogenous H2O2, thus suppressing the CSCs and reducing the expression of CD47." (PMID 38699238, 2024). "(B) Tumor growth curve of projected tumor area versus days after tumor challenge, with B16F10 sgCtrl cells (expressing wild-type [WT] levels of CD47)." (PMID 38805560, 2024). "Combination therapy of anti-CD47 antibodies and STING agonists increased the macrophage polarization to M1-phenotype, reduced tumour immunosuppression, and inhibited the orthotopic GBM growth." (PMID 39049995, 2024). "In preclinical models, the administration of anti-CD47 monoclonal antibodies has shown impressive results with GBM and other tumor models." (PMID 39194679, 2024). "This study showed that elevated expression levels of CD47, CD68, and CD163 in tumor tissues are significantly correlated with poorer OS and PFS in patients with NPC." (PMID 39682556, 2024). "The mechanism by which elevated CD47 expression leads to improved survival in these cancers is unknown, but it is not consistent with the ‘don’t eat me’ hypothesis, which predicts poorer survival due to decreased innate immune clearance of tumor cells bearing high CD47." (PMID 39201643, 2024). "Here, we found that hypoxia-induced ZEB1 expression is closely correlated with CD47-SIRPα axis activity in CSCC, which enables cancer cells to evade phagocytosis by macrophages and promotes tumour progression." (PMID 38183060, 2024). "Survivors from this second tumor challenge were once again challenged, this time with untreated B16F10 CD47 KO." (PMID 38805560, 2024). "Depleting CD47 in GBM cells has shown a significant increase in macrophage phagocytosis and inhibition of GBM tumor growth." (PMID 38275876, 2024).
tumor (continued). "We compared ISB 1442 to clinically validated monospecific antibodies, anti-CD38 (daratumumab) and anti-CD47 (hu5F9, magrolimab) in several potency assays with tumor cell lines expressing varying levels of CD38 and CD47." (PMID 38448430, 2024). "TG-1801 is a bispecific antibody designed with one arm blocking CD47 and the other arm binding to CD19 to accurately identify tumor cells." (PMID 38464520, 2024). "To investigate if CD36 and CD47 can be more widely used as biomarkers for other cancer types, we measured CD36 and CD47 expression in tumor microarrays (TMA) from multiple tumor types." (PMID 39627379, 2024). "Blocking CD47 with monoclonal antibodies or soluble SIRPα-Fc can trigger macrophage-mediated ADCP and significantly kill tumor cells." (PMID 39379603, 2024). "By interfering with CD47-SIRP-α interaction, SIRP-α-exosomes enhance macrophage phagocytosis whilst increasing the number of tumor cells phagocytosis." (PMID 38281957, 2024). "Among these genes, Cd47 and Clu were downregulated, whereas 31 genes were upregulated in WBM‐treated tumours compared with those in PBS‐treated controls." (PMID 39390760, 2024). "Results showed high CD47 expression on 45.6% ± 5.31% of CD4+ and 53.5% ± 7.51% of CD8+ lymphocytes in adjacent tissues, whereas in tumor tissues, CD47high+ lymphocytes decreased to 26.7% ± 4.16% for CD4+ and 37.7% ± 7.21% for CD8+." (PMID 39652550, 2024). "However, tumors evolve quickly and often acquire immune escape mechanisms that may include (a) inhibition of tumor phagocytosis via upregulation of CD47 ‘don’t eat me’ signal, (b) interference with the activities of the complement or NK cells, or (c) clonal escape through antigen downregulation." (PMID 38448430, 2024). "To verify the phagocytosis of tumor cells by macrophages, we detected the capability of BMDM for phagocytosis in a co-culture system, in which CM-DiI-labeled BMDM were cultured with CD47-knockdown B16F10 cells." (PMID 38491004, 2024). "In this work, using IFN-I and IFN-II receptor knockout tumor models, we evaluate the role of IFN responsiveness of tumor cells during CD47-SIRPα blockade therapy." (PMID 38982116, 2024). "The blockade of FAO using etoximir, an inhibitor of a key enzyme in the FAO pathway, synergized with anti-CD47 to strongly increase GBM phagocytosis and decrease tumor volume." (PMID 39194679, 2024). "The anti-CD47 nanobody facilitated significant phagocytosis of the U937 and MCF7 tumor cell lines while also inducing apoptosis in the U937 cells both ex vivo and in vivo in mouse xenotransplants." (PMID 38247566, 2024). "Although not required by the study protocol, paired pre- and on-study tumor tissue samples were voluntarily obtained from 7 patients and were analyzed by IHC for expression of CD36, CD47 and TSP-1." (PMID 38218979, 2024). "(C) Tumor growth curve of projected tumor area versus days after tumor challenge, with B16F10 CD47 KO cells." (PMID 38805560, 2024). "The expression levels of CD47 and TIGIT in tumor tissues (n = 115) were significantly higher than those in normal brain tissues (P = 0.0073, P = 0.0064)." (PMID 38404571, 2024). "In tumor cells with high expression of EGFR, the expression levels of CD47 are also upregulated, leading to enhanced growth and immune evasion capabilities." (PMID 39223632, 2024). "CD38/CD47 BsAbs preferentially bound to CD38+/CD47+ Reh cells, indicating that compared to CD47 therapeutic Abs, BsAbs have lower potential for on-target, off-tumor effects in vivo." (PMID 38983860, 2024). "In hSIRPα/CD47 transgenic mice, NILK-2401 treatment at 30 mg/kg IP twice/week significantly suppressed tumor growth of MC38-hCEACAM5/hCD47, with a TGI of 84.3% at d22 (i.e., 1st day of euthanasia due to tumor volume >1500 mm3)." (PMID 38720892, 2024). "Immunohistochemical analysis showed that the expression levels of CD47 and TIGIT in tumor tissues were significantly higher than those in normal brain tissues." (PMID 38404571, 2024).
tumor (continued). "Using IF double staining of vascular endothelial cells with CD31, α-SMA, and NG2, it was discovered that targeting CD47 significantly increased the coverage of α-SMA+ wall cells and NG2+ pericytes in tumor vascular endothelial cells." (PMID 38398223, 2024). "Among the mAbs studied, the anti-CD47 mAb and the CD40 agonist have demonstrated agonistic properties that reprogram TAMs to produce potent anti-tumor activities." (PMID 39169402, 2024). "Our study, using PLA technology, found a significant interaction between CD47 and VEGFR, CD36, potentially impacting angiogenesis and cell metabolism within the tumor microenvironment, promoting tumor cell survival and proliferation." (PMID 39652550, 2024). "In recent studies, programmed E. coli Pir1+ was used to secrete a CD47-neutralizing nanobody (nb) using a synchronized lysis circuit (SLC), which initiates cell lysis based on the abundance of bacteria in the tumor." (PMID 39594765, 2024). "Further research has confirmed the efficacy of CD47 blockade agents and CCR2 inhibitors in slowing tumor growth and modulating the tumor microenvironment." (PMID 38665428, 2024). "Interaction of CD47 with SIRPA inhibits the phagocytic activity of macrophages, overcoming the expression of ‘eat me’ signals and help tumor cells to evade macrophage surveillance." (PMID 39312740, 2024). "Results showed significant anti-tumor activity due to the synergistic effect of simultaneous dual targeting of HER2 and CD47 leading to antibody-dependent cellular phagocytosis." (PMID 39660126, 2024). "BCMA/CD47-directed UCAR-T cells demonstrated excellent antitumor activity against MM and prolonged the survival of tumor-engrafted NCG mice in vivo." (PMID 38783333, 2024). "By blocking CD47, the suppression of cytotoxic CD8 + T cell function is alleviated, thereby sustaining the anti-tumor response." (PMID 38720108, 2024). "Since the tumor grade accounts for one of the most reliable prognostic factors in STS, we evaluated CD47 abundance in G1 + G2 and G3 tumors." (PMID 38493445, 2024). "It has been demonstrated that hypoxia alters the levels of immune checkpoints like CTLA-4, PD-1/L-1, CD47, and TIM3 to modify the immune cell-induced anti-tumor response, thus suppressing immune surveillance." (PMID 38165484, 2024). "The experimental data from this investigation confirm that the combined targeting of CD47 and CTLA4 enhances immunity against solid tumors in LLC cell-transplanted tumor-bearing mice." (PMID 38398223, 2024). "Within this investigation, we demonstrate that the synergistic effects of anti-CD47 and CTLA4 blockade in immunotherapy yield an efficient anti-tumor impact on NSCLC." (PMID 38398223, 2024). "CD47 plays a pivotal role in the TME, prognosis, and immunotherapy not only through its interactions with macrophages but also with tumor-infiltrating T-lymphocyte cells, particularly CD8 + T cells across various cancer types." (PMID 38720108, 2024). "We observed that the percentage of PLOD2 + SAA1 + tumor cells with high MECRGS scores, as well as the expression of immune checkpoints such as NECTIN2 and CD47, increased in patients who exhibited a partial response (PR) to immunotherapy." (PMID 38951896, 2024). "CD47 expression on CSC from human solid tumors is considered a mechanism of phagocytosis evasion, as a means to overcome immune recognition and allow tumor progression." (PMID 39039104, 2024). "The findings of this study provide compelling evidence that elevated expression levels of CD47, CD68, and CD163 in tumor tissues are significantly correlated with poorer PFS and OS in patients with NPC." (PMID 39682556, 2024). "The bispecific fusion protein SIRPα-VEGFR1 was employed to concurrently target CD47 and VEGF, resulting in significant suppression of tumor growth in the Hu-PDX model." (PMID 38532108, 2024).
tumor (continued). "On laser irradiation, Ce6 can generate reactive oxygen species (ROS) to kill cancer cells directly and induces immunogenic tumor cell death (ICD), which further facilitates the dendritic cell maturation induced by blockade of CD47 by aCD47." (PMID 38560565, 2024). "(C) Geometric mean fluorescence intensity of anti-tumor markers (MHCII and CD86) and pro-tumor markers (CD163 and CD206) on macrophages from immuno-tumoroid cultures of CD47 knockout (KO) B16F10 cells." (PMID 38805560, 2024). "Prior to tumor inoculation, B16F10 CD47 knockout (KO) cells were treated with 2.5 μM MPS1i (reversine) or the equivalent volume of DMSO vehicle control." (PMID 38805560, 2024). "In summary, our results demonstrate that TUG1 regulates PD‐L1 and CD47 in HCC, which further inhibits CD8+ T cells activation and phagocytosis of macrophages, thereby regulating tumor immune escape." (PMID 38981064, 2024). "Anti‐CD8 depleting antibody in conjugation with CD47 × PD‐L1 BisAb treatment resulted in the ablation of CD8+ T cells within the spleen and tumor and led to an outgrowth of AT3‐OVA tumors equivalent to that observed in isotype‐treated mice." (PMID 39584189, 2024). "Therefore by blocking CD47 protein, tumor regression could be attained." (PMID 38892394, 2024). "Innate immune checkpoints, such as the CD47/SIRPα axis, PD-1/PD-L1 axis, and MHC-I/LILRB1 axis, play important roles in tumor-mediated immune escape from the clearance by phagocytosis." (PMID 38383737, 2024). "Tumors with the highest CD47 expression also had decreased numbers of FOXP3+ T-cells, resulting in a favorable cytotoxic to regulatory T-cell ratio post NACT in favor of anti-tumor immunity." (PMID 39138571, 2024). "The concurrent administration of anti-CD47 and anti-VEGF therapies, along with the utilization of a bispecific fusion protein, yielded notable enhancements in the tumor immune microenvironment and a substantial augmentation of the anti-tumor response." (PMID 38532108, 2024). "Blockade of CD47/SIRPα and CD24/Siglec-10 pathways can promote macrophage-mediated phagocytosis of tumor cells." (PMID 38971872, 2024). "Our BsAbs presented potent dose-dependent ADCC activity against CD47+/CD38+ Raji and NCI-H929 cells but negligible ADCC activity against CD47+/CD38– HL-60 cells, indicating low off-tumor toxicity." (PMID 38983860, 2024). "Disruption of the CD47-SIRPA interaction by anti-CD47 antibody shifts macrophage polarization from M1 to M2 status, resulting in insufficient tumor phagocytosis." (PMID 38920727, 2024). "In contrast to CD47, TNF-α induced an increase in PD-L1 expression on tumor cells, however, the level was comparable to that seen on the iTCS-treated MSCs." (PMID 39310770, 2024). "Tumor and blood samples collected from OC patients in the CHIVA trial were assessed for CD47 and TSP-1 before and after neoadjuvant chemotherapy (NACT) and multiplex analysis was used to investigate immune markers." (PMID 39138571, 2024). "Strategies targeting the interaction between CD47 and its receptor SIRP-α have demonstrated promising results either as monotherapies or in combination with other tumor-targeting therapies." (PMID 39712032, 2024). "Here, we explored the role of the tumor microenvironment in regulating MDSC differentiation and immunosuppressive properties via signal-regulatory protein alpha (SIRPα)/CD47 signaling." (PMID 38577107, 2024). "The scRNA-seq analysis revealed that candidate Siglec-9 ligands CD59, CD47, and LGAL3BP were expressed in tumor cells in metastatic tumor tissues derived from patients with CRPC." (PMID 39436703, 2024). "Based on the current paradigm, disruption of the CD47-SIRPA interaction by either anti-CD47 or anti-SIRPA antibody would inhibit the “don’t eat me” signal and thus promote tumor phagocytosis." (PMID 38920727, 2024). "First, a subcutaneous transplantation tumor model of NSCLC cells in mice was established, and this model was treated with a combination of Abs targeting CD47 and CTLA4." (PMID 38398223, 2024).